MYD88 (MYD88 innate immune signal transduction adaptor)
Diseases named in the same sentence as MYD88 in open-access papers (continued):
Sharing a sentence is not in itself a finding about the gene and the disease.
Rotavirus infection (2 papers, 2014 to 2023). Infection with any of the rotaviruses. "The protein-protein interaction (PPI) network analysis suggests that the TLR4/MyD88/NF-κB signalling pathway may be activated and SBP treatment restores the upregulation of inflammatory factors and downregulation of IFN-β due to rotavirus infection." (PMID 37006293, 2023). "Consistent with this, B220+ cell aggregates indicative of ILF were virtually absent in the ileums of MyD88−/− mice and were not induced by GRA treatment or by rotavirus infection." (PMID 24992099, 2014).
sarcopenia (2 papers, 2020 to 2024). Progressive decline in muscle mass due to aging which results in decreased functional capacity of muscles. "We found that the protein levels of TLR4, MyD88 and TRAF6 were significantly increased in three sarcopenia muscle samples, while those of the two NF-κB subunits, p50 and p65 were not increased." (PMID 32226296, 2020). "NLRP3 and Myd-88 are key orchestrators of chemotherapy-related cardiovascular diseases (CTRCD) and sarcopenia; cytotoxic properties are principally mediated by high levels of pro-inflammatory cytokines and chemokines, such as IL-1β, IL-6, IL-8, CXCL-2, TGF-β, IL-18 and others." (PMID 38672567, 2024).
scrapie (2 papers, 2012 to 2022). A fatal disease of the nervous system in sheep and goats, characterized by pruritus, debility, and locomotor incoordination. "Remarkably, contrasting expression patterns were found in the hippocampus of the scrapie-infected sheep, in which TLR2 and MyD88 were downregulated (p < 0.01) and TLR1 showed a tendency towards downregulation (p < 0.1)." (PMID 35408945, 2022). "In the thalamus, TLR6, MyD88, and CD36 were significantly upregulated in the scrapie-infected group (p < 0.05), while TLR2 and TLR3 displayed a tendency towards upregulation (p < 0.1)." (PMID 35408945, 2022). "Our findings in the hippocampus of scrapie-infected sheep reveal an opposite pattern compared with other analyzed brain areas, with the downregulation of TLR1, TLR2, and MyD88 and no cytokine alterations." (PMID 35408945, 2022). "Pathogenic changes in prion disease appear to be independent of MyD88, a signaling intermediate for several TLR family members, as ablation of this molecule did not lead to changes in the incubation periods, and neuropathological profiles of scrapie-infected mice." (PMID 22363497, 2012).
serous ovarian cancer (2 papers, 2020 to 2024). "In high-grade serous ovarian cancer (HGSOC), high expression of MyD88 is associated with advanced stage (p < 0.001) cancer and moderately associated with shorter overall survival (HR: 1.13; 95% CI: 1.01–1.26; p = 0.04)." (PMID 38785969, 2024). "However, in low-grade serous ovarian cancer (LGSOC), high expression of MyD88 is associated with better survival (HR: 0.49; 95% CI: 0.29–0.84; p = 0.009)." (PMID 38785969, 2024). "OVCAR-3 cells due to their TLR4 positivity and as a representative model of serous ovarian cancer were subsequently transfected with siRNA targeting TLR4 or MAD2 and then TLR4, MAD2 and MyD88 expression levels were assessed." (PMID 33370338, 2020).
tauopathies (2 papers, 2023 to 2026). "This study reveals the TLR2/MyD88/NF-κB pathway as the potential link between the signature prerequisite events of progressive neurodegeneration in tauopathy brains: tau aggregation and glial inflammation." (PMID 37552543, 2023). "Therefore, blocking TLR2/MyD88/NF-κB–mediated inflammation with the synthetic peptide wtTIDM holds potential therapeutic value against AD, PSP, FTD, CBD, and other tauopathies." (PMID 37552543, 2023). "While AMI treated P301S mice demonstrated significant decrease in the levels of MYD88, NF-KB, TNF-α and IL-22 by 52% (P < 0.0001, F = 770.9), 54% (P < 0.0001, F = 794.5), 49% (P < 0.0001, F = 385.6) and 39% (P < 0.0001, F = 668.8) respectively when compared to tauopathy model." (PMID 41484454, 2026).
toxoplasmosis (2 papers, 2015 to 2021). A parasitic disease contracted by the ingestion or fetal transmission of toxoplasma gondii. "During experimental toxoplasmosis, T-cell-intrinsic MyD88 deficiency severely affects Th1 responses and impairs resistance." (PMID 26367276, 2015). "Mice deficient in the adapter molecule MyD88 are acutely susceptible to toxoplasmosis." (PMID 33767699, 2021).
ulcer (2 papers, 2014 to 2025). "In the ulcer group, MyD88 levels were elevated, signifying an exacerbated inflammatory condition, while the notable rise in TLR-2 levels further emphasizes the intensified inflammatory response." (PMID 40563542, 2025). "Our findings indicated significant elevations in TLR-2/MyD88 levels in the ulcer group." (PMID 40563542, 2025). "A direct comparison between the ulcer + OMP and ulcer + OMP-NS groups revealed that the OMP-NS formulation significantly decreased levels of HMGB1, NLRP3, NF-κB, TLR-2, MyD88, IL-1β, IL-6, and TNF-α." (PMID 40563542, 2025).
vaginitis (2 papers, 2024 to 2026). A non-infectious or infectious inflammatory process affecting the vagina. "Additionally, the study elucidated that BEPD regulates vaginitis and enhances vaginal barrier function in VVC mice by inhibiting the release of S100A8/A9 and downregulating the TLR4/MyD88/NF-κB signaling pathway." (PMID 38794163, 2024).
Abdominal obesity (1 paper, 2019). Excessive fat around the stomach and abdomen. "As the two groups were matched on abdominal fat, it looks that gene expression levels of TLR2, MyD88 and NFĸB are highly related to abdominal obesity than to healthy or unhealthy metabolic state." (PMID 31272370, 2019). "Serum concentration of IL-1β, FFAs, and mRNA expression levels of TLR2, MyD88, and NFĸB may be resulted from abdominal obesity and not be related to the presence or absence of metabolic health." (PMID 31272370, 2019).
acute monocytic leukemia (1 paper, 2013). Acute monoblastic leukemia (AML-M5), is one of the most common subtypes of acute myeloid leukemia (AML) that is either comprised of more than 80% of monoblasts (AML-M5a) or 30-80% monoblasts with (pro)monocytic differentiation (AML-M5b). "In addition, the human acute monocytic leukemia cell line (THP-1) required signaling through Syk and Myd88 for inflammasome priming when infected with A. fumigatus." (PMID 24340123, 2013).
acute pharyngitis (1 paper, 2024). An acute and painful inflammatory process that affects the pharynx. "Resveratrol was shown to inhibit the protein expression of TLR4, MyD88, and p‐NF‐κB while increasing the abundance of p‐IκB in animal models of acute pharyngitis." (PMID 38378891, 2024).
adenovirus infection (1 paper, 2010). "Similarly, expression of IL-6 after intravenous administration of adenovirus or adenovirus infection of bone marrow macrophages was dependent on Tlr9 and Myd88, respectively." (PMID 20419141, 2010).
adrenocortical tumors (1 paper, 2024). "In our MEN1 patients with adrenocortical tumors, among the cascades with altered genes, one small pathway—with 18 nodes—was identified, i.e., WP3877—the MYD88 distinct input–output pathway." (PMID 38256138, 2024).
alcoholic hepatitis (1 paper, 2023). Acute hepatitis resulting from ingestion of alcohol. "Therefore, long-term alcohol intake might induce strong inflammatory responses via the Myd88 route and thereby cause alcoholic hepatitis." (PMID 37240190, 2023).
anal prolapse (1 paper, 2014). "In contrast, mice with defects in MyD88 signaling develop more severe bacterial infection and bacterial induced disease, as evidenced by results showing gastrointestinal tract bleeding, and development of anal prolapse after bacterial inoculation and higher mortality rate." (PMID 25010669, 2014).
appendicitis (1 paper, 2017). Acute inflammation of the vermiform appendix. "TLR4/MYD88/NF-κB signaling pathway was activated in acute phase of appendicitis." (PMID 29029533, 2017). "This study was conducted to evaluate the immune impact of mimic endoscopic retrograde appendicitis therapy and appendectomy on rabbits of acute suppurative appendicitis and to determine whether TLR4/MYD88/NF-κB signaling pathway was activated in this process." (PMID 29029533, 2017).
arteriosclerosis (1 paper, 2020). A vascular disorder characterized by thickening and hardening of the walls of the arteries. "We measured expression of TLR4, TIRAP, MyD88, TRAF6, p38, NEMO, and IRF5 to test the anti-arteriosclerosis effect of corilagin." (PMID 32849545, 2020).
astrocytomas (1 paper, 2021). "Our transcriptomic data of U87MG cells 12 h after LPS stimulation and the TCGA RNASeq dataset of astrocytoma showed upregulation of genes related to inflammasome and ripoptosome pathways, namely MYD88, NLRP3, RIPK1 and RIPK3, and also SRF, JUN and IL1B, the downstream regulated genes." (PMID 33446690, 2021). "In fact, significant upregulations of MYD88, SRF, JUN, IL1B, TRIF, RIPK1, NLRP3 were detected in GBM cases compared to lower grade astrocytomas (AGII and AGIII)." (PMID 33446690, 2021).
bacterial meningitis (1 paper, 2021). Inflammation of the membranes surrounding the brain and spinal cord due to a bacterial infection. "In previous reports, the MyD88/NF-κ B signaling pathway could cause neurological injury in bacterial meningitis and melatonin inhibits NF-κ B-driven signaling for protective and anti-inflammatory action in the LPS-stimulated RAW 264.7 and BV2 cells." (PMID 33808027, 2021).
behavioural disorders (1 paper, 2016). "Additionally, studies of neurobiology have shown that MyD88 defects can cause cognitive and behavioural disorders in mice." (PMID 27707937, 2016).
bipolar disorder (1 paper, 2014). A disorder of the brain that causes unusual shifts in mood, energy, activity levels and the ability to carry out day-to-day tasks. "In bipolar disorder, protein and mRNA levels of neuroinflammatory markers (IL-1β, IL-1R, MYD88, NF-kB1) and of activated microglia and astroglial markers (GFAP, NOS2, c-Fos, and CD11b) also were significantly higher than in control cortex." (PMID 25329999, 2014).
bleeding (1 paper, 2019). "To confirm the effect of TXA on the Heme/MyD88/TNF axis after CNS bleeding as previously reported, we performed a Western blot analysis for MyD88 and NF-κB p65." (PMID 31358003, 2019).
brain aneurysm (1 paper, 2022). A congenital or acquired aneurysm within the cranium. "It has been shown that the pathway involving TLR4 and MyD88 promotes tissue remodeling and rupture of a brain aneurysm." (PMID 35655323, 2022).
bronchitis (1 paper, 2015). An acute or chronic inflammatory process affecting the bronchi. "The extent of lung inflammation was much lower in Myd88-/- mice at 6 hours (P<0.005 versus WT mice), caused by reduced interstitial inflammation, endothelilitis, bronchitis and edema." (PMID 25700108, 2015).
central nervous system infections (1 paper, 2023). "MYD88 signalling is critical for the control of both innate and adaptive immune responses to various central nervous system infections." (PMID 36414820, 2023).
cervical tumor (1 paper, 2022). "Studies have indicated that inhibiting the TLR4/MyD88/NF-B and Wnt/β-catenin pathways inhibits the growth of cervical tumor.." (PMID 36185280, 2022).
cholestasis (1 paper, 2023). Impairment of the bile flow caused by obstruction within the liver, or outside the liver in the bile duct system. "Our outcomes revealed that the binding free energy of FTA and receptors was less than −5.0 kcal/mol, indicating that FTA may bind these receptors and regulate TLR4/Myd88/NF-κB signaling, thereby improving liver damage caused by cholestasis." (PMID 37432229, 2023). "Substantial evidence showed that inhibition of the TLR4/MYD88/NF-κB inflammatory pathway played a crucial role in the prevention and treatment of cholestasis." (PMID 37432229, 2023). "More importantly, by combining the outcomes of the PPI network, GO and KEGG analysis, we speculated that FTA could ameliorate cholestasis by acting on important targets such as TRL4, MYD88, NF-KB1, and MMP-2." (PMID 37432229, 2023).
chorioamnionitis (1 paper, 2025). A morphologic finding indicating inflammation of the fetal sac membranes. "At the maternal–fetal interface, chorioamnionitis activates innate immune pathways in the placenta and membranes via TLR2/TLR4 recognition of Gram-positive or Gram-negative pathogen-associated molecular patterns (PAMPs), triggering the MyD88–NF-κB signaling cascade." (PMID 41102816, 2025).
chronic hepatitis (1 paper, 2010). An active inflammatory process affecting the liver for more than six months. "In the liver, TLR4 and MyD88 are required for the development of fibrosis in chronic hepatitis." (PMID 20871832, 2010).
coccidioidomycosis (1 paper, 2020). A fungal infection caused by Coccidioides immitis. "Despite the unchanged cytokine response by BMDCs, MyD88−/− and MyD88/TRIF−/− mice were more susceptible than controls to coccidioidomycosis." (PMID 32545735, 2020).
coccidiosis (1 paper, 2022). A parasitic infection caused by Coccidia. "Among genes that have been reported to be expressed in association with innate immunity responses in chickens infected by coccidiosis are TLR-4, TLR-15, MyD88, and nuclear factor kappa B (NF-κB)." (PMID 36230268, 2022).
delirium (1 paper, 2026). A disorder characterized by confusion; inattentiveness; disorientation; illusions; hallucinations; agitation; and in some instances autonomic nervous system overactivity. "COMT, MYD88, and CYP1B1 were identified as key candidate genes underlying opioid-associated delirium." (PMID 42307217, 2026).
dry eye (1 paper, 2023). "Expression of NF-kB associated or mediated inflammatory factors that have been found to increase or contribute to dry eye pathogenesis, including myd88, cytokines il12a, il12b (a subunit shared by IL-23 and IL-12), ltb and chemokine ccl2, was evaluated by PCR." (PMID 37036417, 2023).
ductal adenocarcinoma (1 paper, 2019). "MiR-940 has also been demonstrated to inhibitpancreatic ductal adenocarcinoma growth through targeting MyD88." (PMID 31085718, 2019).
dyslipidaemia (1 paper, 2021). "In agreement with previous reports, we show that MyD88-cholesterol fed animals display exaggerated dyslipidaemia versus WT-cholesterol fed mice." (PMID 34445361, 2021).
eczema (1 paper, 2025). "For instance, drug combinations containing Sophora flavescens–Angelica sinensis inhibit the TLR4/MyD88/NF-κB pathway to treat eczema." (PMID 40612058, 2025).
Enterococcus faecalis infection (1 paper, 2019). A bacterial infection induced by Enterococcus faecalis which is the most prevalent species (along with Enterococcus faecium) cultured from humans, accounting for more than 90% of clinical isolates. "Previous studies have shown that Myd88-knockout in murine bone marrow-derived macrophages show decreased levels of NF-κB p65 subunit (RELA) activation following Enterococcus faecalis infection." (PMID 31726729, 2019).
epididymitis (1 paper, 2023). Inflammation of the epididymis. "Dendritic cells (DCs) and myeloid differentiation primary response gene 88 (Myd88) were associated with epididymitis in rodents." (PMID 37175545, 2023). "We found milder tissue damage, much less fibrosis, and inflammatory response in Myd88−/− UPEC epididymitis." (PMID 37175545, 2023). "The Myd88 signaling pathway, phenotypes of DC subsets, and cytokines were investigated in lipopolysaccharide (LPS)-induced epididymitis in mice." (PMID 37175545, 2023). "Our results show that the expression of MYD88 signaling is significantly enhanced in LPS-induced mouse epididymitis." (PMID 37175545, 2023). "In this study, we explored the role of Myd88 in LPS-induced epididymitis and BMDCs through CRISPR-Cas9 technology." (PMID 37175545, 2023). "In our earlier study, we used UPEC to construct the mice model of epididymitis and detected the expression of Myd88." (PMID 37175545, 2023). "Our previous study found that the tissue damage and inflammatory reactions were rescued in Myd88−/− uropathogenic E. coli (UPEC) epididymitis in mice compared to wild-type mice." (PMID 37175545, 2023). "Our previous study showed reduced inflammation in Myd88−/− UPEC epididymitis." (PMID 37175545, 2023). "Myd88-KO in BMDCs leads to decreased inflammatory factors, indicating a potential role of the MYD88 signaling pathway in DCs involved in the pathogenesis of epididymitis." (PMID 37175545, 2023). "In summary, we found that the MYD88 signaling pathway could modulate the secretion of inflammatory cytokines in DCs, which has an essential role in the pathogenesis of epididymitis." (PMID 37175545, 2023). "This study investigated the role of Myd88 in DCs for epididymitis." (PMID 37175545, 2023). "However, systemic Myd88 knockout cannot explain the regional response to infection and molecular mechanisms in the pathogenesis of epididymitis." (PMID 37175545, 2023). "There was no significant increase in Myd88 expression in UPEC-infected epididymitis." (PMID 37175545, 2023).
Erythema (1 paper, 2024). Redness of the skin, caused by hyperemia of the capillaries in the lower layers of the skin. "Associated with facial erythema, joint pain, anti-dsDNA antibody and anti-IgG antibody.Targeting DNMT1 to inhibit MyD88 methylation and promoting TLR-mediated cellular inflammatory responses." (PMID 39835138, 2024).
esophageal carcinoma in situ (1 paper, 2024). "We confirmed these results in a mouse model of 4NQO-induced esophageal carcinoma in situ and further identified epithelial–mesenchymal transition (EMT) occurrence and TLR4/Myd88/NF-κB pathway activation in mouse esophageal tumors." (PMID 38834834, 2024).
esophageal squamous cell carcinoma (1 paper, 2017). Esophageal squamous cell carcinoma (ESCC) is a type of esophageal carcinoma (EC) that can affect any part of the esophagus, but is usually located in the upper or middle third. "One of the key central nodes in the top DEGs in Myd88−/− mice at both 25 and 47 weeks post-infection was guanylate-binding protein 2 (Gbp2), which is considered a potential marker for esophageal squamous cell carcinoma." (PMID 28201999, 2017).
fetal growth restriction (1 paper, 2025). A fetus that does not grow beyond the 10th percentile of conventionally accepted weight for gestational age. "Moreover, fetal growth restriction (FGR) upregulates the level of MyD88 protein in maternal rats’ serum, and the suppression of MyD88-related pathways can alleviate FGR." (PMID 40218311, 2025).
Flavivirus Infections (1 paper, 2017). Infections with viruses of the genus FLAVIVIRUS, family FLAVIVIRIDAE. "Despite the upregulation of toll gene expression induced by flavivirus infection, the gene encoding down-stream MyD88, which is activated via toll engagement, was significantly downregulated at 72 and 120 hpi following infection with all three pathogens." (PMID 28202075, 2017).
functional dyspepsia (1 paper, 2025). "In brief, CRP could attenuate dyspepsia by reducing the activation of inflammation-related TLR4/MyD88 and MAPK signaling pathways and by mediating gut microbial structure and composition." (PMID 40017602, 2025).
gastric disease (1 paper, 2021). "Histological analysis revealed that Myd88−/− genotype displays the worst gastric disease following infection, followed by the DKO genotype." (PMID 33477306, 2021).
gastric lymphoma (1 paper, 2022). An extranodal lymphoma that arises from the stomach with the bulk of the mass located in the stomach. "PD‐L1 expression with an H‐score >1 was found in 8/51 (16%) of the mutated cases harboring a MYD88 mutation and co‐expressing PD‐L1, with only two cases in each of the CNS, ENT, and skin, one case of PMBL, and one gastric lymphoma." (PMID 36051079, 2022).